SSTR2 (somatostatin receptor 2)
Diseases named in the same sentence as SSTR2 in open-access papers (continued):
Sharing a sentence is not in itself a finding about the gene and the disease.
tumor (continued). "The tumor uptake of [203Pb]Pb-PSC-PEG2-TOC was almost completely blocked by co-administration of excessive unlabeled peptide, indicating that the high tumor uptake of [203Pb]Pb-PSC-PEG2-TOC is mediated by specific binding to SSTR2." (PMID 37955792, 2024). "Immunohistochemical (IHC) staining analysis of SSTR2 and FAP expression in tumor tissues." (PMID 39770488, 2024). "First, since our agent relies solely on SSTR2 expression in the tumor, variability of SSTR2 expression in pNETs and physiologic SSTR2 expression in normal pancreatic tissue can confound the interpretation of imaging findings." (PMID 38267640, 2024). "However, when comparing the tumor uptake of [111In]In-eTFC-01 and [64Cu]Cu-MMC(IR800)-TOC, it must be taken into account that the AR42J cell line is known to have a 3-fold higher SSTR2 expression than the NCI-H69 cell line." (PMID 38775990, 2024). "SSTR3, SSTR2, and SSTR5 expression in tumor tissues was analyzed by qRT-PCR and Western blot." (PMID 38612419, 2024). "Therefore, the objective of this study is to create a dual-receptor-targeted peptide heterodimer probe that simultaneously targets SSTR2 and FAP, with the expectation of improving tumor detection sensitivity and extending tracer uptake and retention time." (PMID 39770488, 2024). "99mTc octreotide SPECT yielded no pertinent findings, and the tumor was considered somatostatin receptor 2 negative." (PMID 39125476, 2024). "Interestingly, in the present case, both SSTR2 and IGF-1R appeared on the plasma membrane and in the cytoplasm, showing immunoreactivity not only in tumor cells but also in peritumoral structures (blood vessels and stromal cells)." (PMID 39238765, 2024). "One such protein is Somatostatin receptor 2 (SSTR2), which promotes tumor growth and survival." (PMID 38203275, 2023). "This indicated that tumor recurrence after the initial regression upon administering PRRT + AZD7648 was not initiated from SSTR2-negative cells present in the tumor, but rather due to a different mechanism of therapy resistance." (PMID 37351169, 2023). "Although debates on the correlation of SSTR2 with NEPC exist in the literature, we believe that the main reason perhaps arises from the heterogeneous and dynamic nature of the innervated tumor microenvironment (TME), which makes biopsy-based IHC results either inaccurate or unrepresentative." (PMID 36839802, 2023). "The tumor-to-organ ratio of 177Lu-DOTATATE uptake showed at least a 2-fold increase in CI-994 (5 mg/kg)-treated QGP-1 tumors compared with control tumors, which represents a key feature for imaging contrast in SSTR2-targeted PRRT." (PMID 37487000, 2023). "Out of which, the SSTR2 and SSTR5 have gained significant attention due to their role in mediating the inhibition of growth hormone and antiproliferative effects of somatostatin on tumor growth." (PMID 37770425, 2023). "In the thyroid, SSTR2 has drawn great attention because it binds strongly to OCT and Lanreotide, as well as pasireotide, which has frequently been used in the treatment and detection of tumours." (PMID 38203605, 2023). "Despite evidence that SSTR expression is highly variable between individuals, changing SSTR2 expression for tumors did not result in substantial different tumor uptake predictions." (PMID 36735114, 2023). "SSTR2-inducing effects of DMNT and HDAC inhibitors are known to vary among different tumor models." (PMID 36593963, 2023). "Among the factors that influence treatment response, the degree of SSTR2 expression of tumour cells at SSTR scintigraphy (i.e., Krenning score of 3 and 4) is critical, along with the site of the primary tumour, tumour burden, tumour grading, and imaging uptake on PET scan." (PMID 36980746, 2023). "Tumor growth was not slowed in the 177Lu-DOTATATE–only treatment group, potentially due to SSTR2 deficiency." (PMID 37487000, 2023).
tumor (continued). "Similarly, another study demonstrated that the DRD2 agonist BIM53097 and SSTR2 agonist BIM23120 had antiproliferative effects on both the spheres and tumor tissues in about half of the studied NF-PitNETs." (PMID 37109772, 2023). "The primary limitation of all of these approaches is the requirement for Sstr2 expression on the tumor cell surface, as often Sstr2 expression is either initially lacking or becomes downregulated with agonist-directed therapy." (PMID 36965619, 2023). "It has also been shown that the heterogeneous SSTR2 expression seen on 68Ga-DOTATOC PET/CT differed depending on the primary and metastatic sites, and that the coefficient of variation (CoV) was higher in NEN metastases than in the primary tumours." (PMID 36980746, 2023). "Importantly, our findings suggest that a therapeutic approach aimed to interfere with hsa-miR-5096 activity, inhibiting its targeting of SSTR2 3’-UTR sequences, would enhance SSTRs expression and sensitize tumor cells to PRRT or other SSTR-targeted therapies." (PMID 37287922, 2023). "The two tumor models used in the small animal imaging evaluation were established by wild-type PC3 cells with high expression of SSTR2, and by PTP1B-silenced PC3 cells (PC3_sgPTP1B) with low expression of SSTR2." (PMID 36839802, 2023). "Additionally, G protein signaling mediated by Octreotide and ITF2984 was analyzed in mouse corticotroph tumor AtT-20 cells, which endogenously express GIRK1/2 channels as well as SSTR2 and SSTR5 receptors." (PMID 37444563, 2023). "Two of the most effective treatments for patients with NET (i.e., SSAs and peptide radionuclide therapy) depend on the expression of SSTR2 and SSTR5 on the tumor cell surface, and these SSTRs are crucial therapeutic targets for SSAs and peptide radioreceptor therapy in NET treatment." (PMID 36555512, 2022). "For one mouse in the 2 × 15 = 30 MBq group, tumor volume reduction did not occur after treatment, and the expression of SSTR2 in this tumor tissue was lower than for the other tumor tissues in this group." (PMID 35008397, 2022). "Immunohistochemistry analysis for SSTR2 expression levels in tumor tissue confirmed the RT-qPCR results, demonstrating no evident increase in SSTR2 protein expression after VPA treatment." (PMID 35057069, 2022). "In animals, a statistically significant increased [177Lu]Lu-DOTATATE tumoral uptake was observed when VPA was administered eight hours before [177Lu]Lu-DOTATATE administration, but increased tumor SSTR2 expression levels were lacking." (PMID 35057069, 2022). "The percentage of LH + and SSTR2 + cells was not significantly different between S100BHigh and S100BLow tumour areas." (PMID 35139928, 2022). "We also found that in all patients in whom a 68Ga-DOTATATE PET scan was available and the Krenning score was 3, the TET also expressed SSTR2 while in almost all cases of 68Ga-DOTATATE PET scan Krenning score 1 or 2 the tumor was negative for SSTR2 expression." (PMID 35198446, 2022). "Without PEN-221 treatment, Jurkat-SSTR2 and Jurkat-NT tumors showed progressive and comparable tumor growth, indicating that the expression of SSTR2 has no impact on cell growth." (PMID 36463361, 2022). "Besides, co-expression of SSTR2 and SSTR3 modulates anti-proliferative signaling and apoptosis, which is also benefit to tumor biology research." (PMID 35053382, 2022). "In these 5 tumours, the percentage of ERα-expressing and LH-expressing cells seemed to show less intratumoural heterogeneity than S100B-expressing, FSH-expressing, Ki67-expressing, and SSTR2-expressing cells." (PMID 35139928, 2022). "We found a positive correlation between the mRNA levels of CHST7, Pit-1, and SSTR2, which suggests that CHST7 may function at the crossroads of tumor cell differentiation." (PMID 35954244, 2022).
tumor (continued). "The introduction of SSTR2 antagonists represents an important development in the field of NET imaging, as they bind to more receptors than SSTR2 agonists and therefore provide a higher tumor uptake, with better NET visualization." (PMID 34215673, 2022). "SSTR2 expression, SSTR5 expression, and the SSTR2/5 ratio did not correlate with the tumor volume change rate following SSA treatment." (PMID 36435867, 2022). "Interestingly, 68Ga-DOTA-JR11 and -LM3, which have drastically lower affinities for SSTR2 (approximately 150-fold and 60-fold, respectively) than 68Ga-DOTATATE, showed higher tumor uptake." (PMID 36569154, 2022). "The overexpression of the tumor targets SSTR2 in NETs can increase the effectiveness of RLT without increasing the toxicity profile." (PMID 35626105, 2022). "The presence of SSTR2 on NETs has led to the use of synthetic somatostatin analogs (eg, octreotide and lanreotide) and radiolabeled somatostatin analogs (eg, 111In-pentetreotide [Octreoscan] and 177Lu-DOTATATE) for tumor localization and treatment." (PMID 35058882, 2021). "No SSTR2-mediated binding was observed in frozen tumor sections, possibly due to disruption of the cells in the process of sectioning the tissue before exposure to the contrast agent." (PMID 33970376, 2021). "Histological examination showed the resected tumor expressed SSTR2, whereas non-fluorescent non-tumorous background muscle tissue showed no SSTR2 expression, in line with absence of fluorescence." (PMID 33768405, 2021). "All the [68Ga]Ga-DOTANOC-avid tumors expressed SSTR2, and the only [68Ga]Ga-DOTANOC negative tumor did not express SSTR2." (PMID 35008325, 2021). "When research using these two SSTR2 radiolabeled compounds were expanded to four advanced NET patients, the 177Lu-DOTA-JR11 provided 1.7–10.6-fold higher tumor uptake dose compared to the agonist, 177Lu-DOTA-octreotate, which resulted in a partial remission in half of the enrolled patients." (PMID 34093445, 2021). "Of the tumors that expressed SSTR2, 9 had a Krenning score of 4, 13 tumors had a Krenning score of 3, and only the tumor with a Krenning score of 2 did not express SSTR2 (Spearman’s rho 0.405, p = 0.043)." (PMID 35008325, 2021). "Increased intra-tumoral SST expression may in turn lead to anti-secretory and anti-proliferative effects, whereas increased SSTR2 expression could improve tumor visibility with SSTR-scintigraphy and enhance tumor response to (radiolabeled) SSAs." (PMID 33085037, 2021). "Three groups of primary tumors (score 1–3, no primary tumor had score 0) were established and SSTR2 expression in matched metastases was assessed." (PMID 33922482, 2021). "Together, these findings suggest a potential difference in effect between mifepristone and relacorilant, in which relacorilant-induced increased SSTR2 expression on the tumor can increase the efficacy of endogenous and exogenous somatostatin on ACTH secretion and tumor proliferation." (PMID 35058882, 2021). "The median score was 0 for each molecular subgroup of GIST indicating low or absent expression of SSTR2 in the tumour tissue in all GIST tumours reviewed." (PMID 33443647, 2021). "The in vitro effects of mifepristone on SSTR2 expression in corticotroph tumor cell lines have not been studied." (PMID 35058882, 2021). "SSTR2 is widely considered the most important mediator of SST antiproliferative functions, which include induction of cell cycle arrest and apoptosis as well as inhibition of tumor angiogenesis and growth factor (e.g., VEGF and IGF-1) expression." (PMID 34680266, 2021). "(Online Resource 3) The CH-157MN model thus provided an additional negative control for SSTR2-mediated tumor uptake." (PMID 33768405, 2021). "ACTH and serum cortisol decreased during concomitant relacorilant and octreotide LAR treatment, suggestive of an increased effect of octreotide LAR due to upregulation of SSTR2 without tumor shrinkage." (PMID 35058882, 2021).
tumor (continued). "CH-157MN had no tumor specific tracer staining due to absence of SSTR2 expression, thereby serving as a negative control." (PMID 33768405, 2021). "The actin binding protein filamin A (FLNA) is required for somatostatin receptor 2 (SSTR2) and dopamine receptor 2 (DRD2) expression and signaling in GH- and PRL-secreting PitNETs, respectively, playing a role in tumor responsiveness to somatostatin receptors ligands and dopaminergic drugs." (PMID 33664708, 2020). "The strong linkage identified in this work between SSTR2+ and NEUROD1+ cells also supports work to date suggesting diverse populations of cellular subtypes in different patients and potentially within the same tumor." (PMID 31413814, 2019). "The limited observed effect of octreotide on tumor shrinkage in that study could be due to SSTR5 being the predominant SSTR expressed (84%), followed by SSTR3 (61%), while SSTR2 was expressed in only 46% of the cases." (PMID 30020466, 2019). "Initial studies using the SSTR2 agonist octreotide showed no or little effect on the tumor growth of clinically defined NFPAs." (PMID 30020466, 2019). "Similarly to our findings on receptor mRNA, higher expression levels of SSTR-2 and SSTR-5 receptor protein were found in OCM-3 tumor cell line, than in OCM-1 cell line detected by western blot." (PMID 29949880, 2018). "Additionally, in the SA group, SSTR2 expression was positively correlated with the reduction of IGF-1 and tumor volume." (PMID 28396686, 2017). "In HCC a negative correlation between tumor diameter and SSTR2 expression intensity of the tumor cells was observed (rsp = −0.319, p = 0.024)." (PMID 29282035, 2017). "Although SSTR2 has its specific endogenous ligand (somatostatin) but it is not much involved in tumor growth inhibition and therapy." (PMID 29029435, 2017). "Using a SSTR2-based reporter, we assessed whether angiotensin II can improve gene expression by adenovirus upon intra-arterial delivery in a rabbit VX2 tumor model." (PMID 26983635, 2016). "Immunohistologically, the tumor cells were positive for antibodies for the neuroendocrine markers, chromogranin A, neural cell adhesion molecule (NCAM), and somatostatin receptor type 2 (SSTR2)." (PMID 25685590, 2015). "The multivariate model also revealed that SSTR2 expression levels may be used as an independent prognostic marker of HCC, as well as tumor TNM-7 stage." (PMID 24137418, 2013). "Interestingly, the active targeting micelles were more effective in H446 tumor than MCF-7 tumor, consistent with the notion of SSTR2-mediated drug uptake and action." (PMID 24300405, 2013). "In the human biopsies of primary bronchial small-cell carcinoma, tumour cells showed high positivity for SSTR2 and normal cells tended to be negative." (PMID 22214480, 2011). "Among somatostatin receptors, SSTR2 has been found to play a critical role in the negative control of cell growth and to act as a tumor suppressor gene for pancreatic cancer and in medullary thyroid carcinoma." (PMID 19365586, 2009). "The overexpression of SSTR2 in NETs has enabled the development and FDA approval of radiolabeled somatostatin analogs, such as (68Gallium) 68Ga-DOTATATE for PET imaging and (177Lutetium) 177Lu-DOTATATE for PRRT, offering precise tumor visualization and effective targeted therapy." (PMID 39857944, 2025). "Although we could not obtain post-everolimus tumor tissue to confirm SSTR2 re-expression directly, several compelling lines of evidence support its plausibility." (PMID 41210247, 2025). "Our study provides compelling evidence that SSTR2 is not merely an overexpressed marker in HCC but may participate in a broader oncogenic signaling network that contributes to tumor progression, invasion, and poor clinical outcomes." (PMID 41002582, 2025). "Moreover, targeting SSTR2 with specific modulators may disrupt the VEGFR, PDGFR, and RAF/MEK/ERK pathways, offering a synergistic approach with sorafenib to inhibit tumor growth and angiogenesis more effectively." (PMID 41002582, 2025).
tumor (continued). "However, to the best of our knowledge, no previously published case of a MeNET demonstrating SSTR2 expression in another organ has been reported where the SSTR2 expression did not lead to a distant tumor diagnosis." (PMID 41246739, 2025). "The variability in staining intensity observed across different patient samples suggests heterogeneous SSTR2 expression within HCC, which may have implications for stratifying patients for targeted therapies and for understanding tumor biology in subgroups with high SSTR2 expression." (PMID 41002582, 2025). "Unfortunately, SST signaling was not analyzed in any of these studies thus not allowing conclusions as to whether SSTR2 signaling crosstalks with TβRII or ALK5 in tumor suppression or with ALK5 in metastasis promotion." (PMID 40134804, 2025). "Tumours not expressing an abundance of SSTR-2 over SSTR-5 subtypes may have reduced response to these agents and may, in fact, experience preferential suppression of glucagon over insulin, leading to hypoglycaemia." (PMID 40697399, 2025). "Importantly, none of the tumour tissues exhibited strong immunoreactivity, although intense SSTR2 expression was observed in the peritumoral area (bottom-panels)." (PMID 40268793, 2025). "Somatostatin receptor 2-directed imaging with 68Ga DOTATATE PET/CT has been suggested as an alternative to 18F-Fluorodeoxyglucose-PET in sinonasal malignancies as it allows for better tumor characterization due to the absence of brain uptake." (PMID 39682120, 2024). "The sstR2-targeting abilityof [18F][natGa]Ga-(SiFA)SeFe-rhTATE2 was also successfully validated by PET in ovo.Further, the biodistribution of [18F][natGa]Ga-(SiFA)SeFe-rhTATE1 and [18F][natLu]Lu-(SiFA)SeFe-rhTATE3 was assessed in AR42J tumor-bearingCD1-nu/nu mice 1 h p.i.." (PMID 39115131, 2024). "Even though so far there is no direct correlation between SSTR2 expression and pericytes in cancer, pericytes help maintain the integrity and functionality in tumour vasculature; therefore, depleting pericytes make blood vessels within the tumour more vulnerable and sensitive to therapies." (PMID 39767203, 2024). "Despite the successful clinical outcomes of radiotracers targeting SSTR2 or FAP, single-receptor recognition may limit their sensitivity for disease detection, especially in early stages, due to tumor heterogeneity and relatively low receptor expression density." (PMID 39770488, 2024). "This could be a sign of SSTR2-expression in SCLC being indicative of immune evasion and increased tumor cell invasiveness 26, contradicting earlier assumptions derived from NETs, which assumed that SSTR2-expression could indicate less aggressive tumors and a potential for favoring apoptosis." (PMID 39310095, 2024). "No Warthin tumor showed a percentage of cells staining for SSTR2 above ≥20%." (PMID 37568733, 2023). "Analysis of the GSE 117852 dataset of 32 PNET samples showed a significant negative correlation between SSTR2 gene expression and mean SSTR2 promoter methylation levels, indicating low mean promoter methylation levels (open chromatin) in tumor samples exhibiting elevated SSTR2 expression." (PMID 37487000, 2023). "SUV is not a direct measure of how many tumor cells express SSTR2." (PMID 35198446, 2022). "However, the rapid blood clearance of such SSTR2 radioligands and the significant accumulation in non-target tissues pose a limit for higher tumor dose delivery and more efficient treatment." (PMID 36145375, 2022). "In addition, an in vivo octreotide loading test or immunostaining with SSTR2 and SSTR5 in tumor tissues may help to further predict the therapeutic response of SSA." (PMID 35265125, 2022). "Indeed, NT-3 cells may be a more suitable tumor cell model than BON and QGP, which is also supported by their higher physiologic levels of SSTR2 and SSTR5." (PMID 36555512, 2022).